PDCD10 (programmed cell death 10)
Diseases named in the same sentence as PDCD10 in open-access papers (continued):
Sharing a sentence is not in itself a finding about the gene and the disease.
glioblastoma (10 papers, 2015 to 2024). The most malignant astrocytic tumor (WHO grade IV). "Due to PDCD10 deficiency, glioblastoma cells become activated and facilitate tumor development." (PMID 36276268, 2022). "Likewise, loss of PDCD10 is also associated with hyper-angiogenesis in glioblastoma (GBM)." (PMID 36497468, 2022). "We previously reported a downregulation of PDCD10 in 85% of a cohort of primary glioblastoma patients." (PMID 39273014, 2024). "We previously reported the downregulation of PDCD10 in primary glioblastoma patients and its tumor suppressor-like function in glioblastoma cells." (PMID 39273014, 2024). "The release of CXCL2 activated CXCR2 and the blockade of CXCR2 signaling hindered macrophage-like cell migration that was triggered by programmed cell death 10 (PDCD10)-overexpressed glioblastoma cells." (PMID 39007996, 2024). "For instance, downregulated PDCD10 in human glioblastoma multiforme (GBM) is accompanied by enhanced malignant phenotypes and activation of Akt pathway." (PMID 37781039, 2023). "PDCD10 absence in the tumor-infiltrating endothelial has reported to activate glioblastoma cells and promote tumor growth." (PMID 37781039, 2023). "PDCD10 (Programmed cell death 10) overexpression in glioblastoma promotes microglia recruitment to the tumor core through elevating cell migration capacity and evokes microglia polarization toward a pro-tumor phenotype with CXCL2-CXCR2 axis signaling." (PMID 37700840, 2023). "According to our previous study, CXCL2-CXCR2 signaling mediated by PDCD10 participates in the crosstalk between glioblastoma cells and microglia/macrophages and promotes tumor growth." (PMID 35963638, 2022). "We previously showed that PDCD10 promotes tumor progression in vivo by enhancing CXCL2-CXCR2 signaling in glioblastoma." (PMID 35963638, 2022). "We previously reported an angiogenic and tumor-suppressor-like function of programmed cell death 10 (PDCD10) in glioblastoma (GBM)." (PMID 32850441, 2020). "Furthermore, PDCD10 downregulation led to the dedifferentiation of glioblastoma cells, as evidenced by increased clonogenic growth, the upregulation of glioblastoma stem cell (GSC) markers, and enhanced neurosphere formation capacity." (PMID 39273014, 2024). "This may, in conjunction with our data on MGMT and MMR genes, elucidate the pivotal role of PDCD10 in mediating TMZ sensitivity in glioblastoma." (PMID 39273014, 2024). "Our data demonstrate the critical role of PDCD10 in the self-renewal of glioblastoma cells." (PMID 39273014, 2024). "On the contrary, PDCD10 was reported as a tumor suppressor in glioblastoma cells." (PMID 35963638, 2022). "In addition to these findings from the immunohistochemistry study in GBM patient sections, we further demonstrated that a knockdown of PDCD10 in glioblastoma cells promoted malignant behaviors of tumor cells in vitro and stimulated tumor growth in vivo by triggering EphB4 kinase." (PMID 39273014, 2024). "As shown in our previous results, PDCD10 participates in the crosstalk between glioblastoma cells and microglia/macrophages and promotes tumor growth by CXCL2-CXCR2 signaling in vivo, which suggests that CXCR2 may play a critical role in aggressive behaviors mediated by PDCD10 in tumors." (PMID 35963638, 2022). "PDCD10 knockdown upregulated MGMT, a key enzyme mediating chemo-resistance in glioblastoma, accompanied by increased expression of DNA mismatch repair genes, and enabled tumor cells to evade TMZ-induced cell-cycle arrest." (PMID 39273014, 2024). "Programmed cell death 10 (PDCD10) plays a crucial role in regulating tumor phenotyping, especially in glioblastoma (GBM)." (PMID 34108959, 2021).
ovarian carcinoma (10 papers, 2020 to 2025). A malignant neoplasm originating from the surface ovarian epithelium. "In summary, our findings suggested that the miR-222-3p/PDCD10 regulatory axis, repressing ovarian cancer cell migration and tumor metastasis, was associated with the EMT signaling pathways." (PMID 32483426, 2020). "In ovarian cancer cells, PDCD10 upregulates Wnt/β-catenin signaling thereby augmenting migration of tumor cells." (PMID 35963638, 2022). "Genome-wide analysis also showed that increased copy number and high expression level of PDCD10 are associated with tumor grade, nodal involvement and advanced FIGO stage in ovarian cancer." (PMID 35963638, 2022). "SNAI2 was found to induce EMT in ovarian cancer through suppressing miR-222-3p transcription and upregulating PDCD10." (PMID 35227285, 2022). "In ovarian cancer, upregulation of programmed cell death 10 (PDCD10) and silencing miR-222-3p microRNA promote carcinoma plasticity, which is mediated by SNAI2." (PMID 34298613, 2021). "suggest that SNAI2’s non-canonical signaling pathway causes EMT in ovarian cancer cells by decreasing miR-222-3p transcription and upregulating PDCD10 expression." (PMID 36591476, 2022). "However, it still needs further study if PDCD10 has an organ-specific role in promoting ovarian cancer metastases." (PMID 32483426, 2020). "Copy number alterations in genes such as PDCD10 and NDUFB9 (amplifications) and NDUFS7 and ZBTB7A (deletions) were also identified, particularly in ovarian cancer, suggesting their contributions to genomic instability." (PMID 40396172, 2025). "The role of PDCD10 in cell survival and proliferation has been confirmed in various types of cancer, including NSCLC, bladder cancer, ovarian cancer, cervical cancer, and prostate cancer." (PMID 38351531, 2024). "Moreover, upregulation and the pro-survival/proliferative effects of PDCD10 were also demonstrated in non-small cell lung cancer (NSCLC), bladder cancer, ovarian cancer, cervical cancer, and prostate cancer." (PMID 36497468, 2022). "PDCD10 was also reported to regulate EMT in hepatocellular carcinoma and ovarian cancer." (PMID 35963638, 2022). "Together, our data indicated a negative correlation between the miR-222-3p/PDCD10 regulatory axis and ovarian cancer metastasis." (PMID 32483426, 2020).
prostate carcinoma (10 papers, 2017 to 2024). A carcinoma that arises from epithelial cells of the prostate gland. "Another study reported that microRNA-103 suppressed tumor cell proliferation by targeting PDCD10 in prostate cancer." (PMID 32850441, 2020). "For example, it is downregulated in prostate cancer and by that virtue enables upregulation of its oncogenic target PDCD10, which promotes proliferation and cellular migration." (PMID 27888798, 2017). "Besides, PDCD10 was identified as the target of CircSMARCA5-miR-432 axis, and was found to promote proliferation, metastasis and glycolysis of prostate cancer cells." (PMID 35963638, 2022). "Further studies showed that ELVOL1, PDCD10, and GNE proteins were also significantly over-expressed in prostate cancer." (PMID 35706452, 2022). "Notably, a recent study reported that PDCD10 can increase the activity and level of LDHA and promote the glycolysis of prostate cancer cells, suggesting its regulatory role in tumor metabolism." (PMID 36497468, 2022).
meningioma (7 papers, 2014 to 2022). A generally slow growing tumor attached to the dura mater. "In the central nervous system, patients harboring heterozygous mutations in PDCD10 displayed a high risk for developing meningioma, suggesting a potential tumor suppressor-like function of PDCD10." (PMID 32850441, 2020). "A particularly exciting discovery is the predisposition of patients with PDCD10 mutations to develop meningiomas in addition to CCMs." (PMID 27896269, 2016). "Several reports in the literature demonstrate that patients with familial PDCD10 mutations have developed late–onset meningiomas in addition to multiple CCMs." (PMID 27896269, 2016). "A recent study has highlighted the possible association of CCM with meningiomas in a large cohort of familial CCM harboring PDCD10 mutations." (PMID 26490252, 2015). "The results of subsequent studies also supported this association, suggesting that PDCD10 depletion may be responsible for the oncogenesis of meningiomas." (PMID 36497468, 2022). "Patients harboring heterozygous mutations of PDCD10 displayed a high risk of developing meningioma." (PMID 32850441, 2020). "It has been recently reported that PDCD10/CCM3 mutation carriers display earlier symptoms' onset, usually before 15 years of age, and higher risk of cerebral haemorrhage during childhood; multiple meningiomas are frequently reported too." (PMID 25354366, 2014). "However, it is currently not clear whether the PDCD10 mutation is a cause of meningioma or not, but if it is a cause of meningioma, how mutant PDCD10 leads to meningioma formation is worth exploring." (PMID 36497468, 2022). "Thus, dysfunctional CSC may not be the primary instigator in meningiomas with mutant PDCD10." (PMID 36497468, 2022).
bladder cancer (4 papers, 2021 to 2024). "Recent reports have indicated that miR-103 inhibits tumor cell proliferation in PCa by targeting programmed cell death protein 10 (PDCD10), while miR-103a-3p is also low in bladder cancer." (PMID 35211152, 2021). "The pro-tumorigenic effect of PDCD10 was also recently reported in lung cancer and bladder cancer." (PMID 35963638, 2022).
colorectal cancer (4 papers, 2016 to 2022). A primary or metastatic malignant neoplasm that affects the colon or rectum. "Downregulation of PDCD10 was associated with chemo-resistance in colorectal cancer cells." (PMID 32850441, 2020). "Furthermore, a recent study suggested that miR-425 regulated tumour progression by directly targeting PDCD10 in colorectal cancer." (PMID 32284738, 2020).
glioma (4 papers, 2015 to 2022). A benign or malignant brain and spinal cord tumor that arises from glial cells (astrocytes, oligodendrocytes, ependymal cells). "In cancers, PDCD10 was also found to promote the recruitment and M2 polarization of glioma-associated micro-glia/macrophages." (PMID 36497468, 2022). "Another report showed that CCM lesions were also associated with neuroglia (the cell of origin of glioma), in which loss of PDCD10 promoted cell survival, cell proliferation, and vascular lesions." (PMID 36497468, 2022). "The loss of endothelial PDCD10, associated with cell apoptosis, stimulates proliferation and inhibits apoptosis to activate glioma cells and promote tumor growth." (PMID 34252885, 2021). "Intriguingly, PDCD10 was even reported to have both tumor-suppressive and tumor-promoting effects in gliomas." (PMID 36497468, 2022). "Similar to the function of PDCD10 in CCM, PDCD10 deficiency seems to promote the cell proliferation, migration, and angiogenesis of glioma." (PMID 36497468, 2022). "Here, we reported for the first time the downregulation of PDCD10 mRNA and protein in a malignancy-dependent manner in gliomas, accompanied by a significant activation of Akt, an important signal protein regulating cell survival and angiogenesis." (PMID 26490252, 2015). "Here we report for the first time that PDCD10 expression at both mRNA and protein levels decreased in a malignancy-dependent manner in glioma." (PMID 26490252, 2015). "Thus, to figure out the precise role of PDCD10 in gliomas, more research in huge clinical cohorts is encouraged in the future." (PMID 36497468, 2022). "A significant downregulation of PDCD10 was found in GBM, the most aggressive glioma, concomitantly accompanied by the activation of Akt." (PMID 26490252, 2015).
brain tumors (3 papers, 2007 to 2022). "While SERPINI1 is predominantly expressed in normal brain and down-regulated in brain tumors, PDCD10 is ubiquitously expressed in all normal tissues but its gene transcription becomes aberrant in different types of cancers." (PMID 17212813, 2007). "In this study, we present evidence showing that while SERPINI1 is predominantly expressed in brain and down-regulated in brain tumors, PDCD10 is ubiquitously expressed in all normal tissues but its gene transcription becomes aberrant in different types of cancers." (PMID 17212813, 2007). "Thus, the PI3K-Akt pathway may also be one of the keys to the negative regulation of tumorigenesis mediated directly by PDCD10 in brain tumors, though further investigation is needed." (PMID 36497468, 2022). "Results from the semi-quantitative RT-PCR indicate that while SERPINI1 expression was negatively correlated with tumor progression, the mRNA level of PDCD10 was not much affected in brain tumor cells." (PMID 17212813, 2007). "More recently, we have discovered that CCM3/PDCD10 is absent in the majority of tumour vessels of GBM, the most common and aggressive brain tumour characterized by massive neo‐angiogenesis." (PMID 28371279, 2017).
colon cancer (3 papers, 2016 to 2024). "For instance, in colon cancer, PDCD10 is upregulated, protecting cancer cells from cisplatin‐induced apoptosis." (PMID 38351531, 2024). "Several lines of evidence have implicated critical roles of PDCD10 in the suppression of ROCK/Rho signaling-mediated phosphorylation of MLC to regulate actomyosin contractility, whose expression is aberrantly up-regulated in metastatic colon cancer cells and pancreatic adenocarcinomas." (PMID 30408026, 2018).
hepatocellular carcinoma (3 papers, 2021 to 2022). A malignant tumor that arises from hepatocytes. "In contrast, in hepatocellular carcinoma (HCC), PDCD10 enhances the catalytic activity of PP2A through a direct or indirect physical interaction, which in turn promotes the dephosphorylation and nuclear translocation of YAP, leading to downstream oncogene expression." (PMID 36497468, 2022).
lung carcinoma (3 papers, 2022 to 2024). "Dysfunction of miR-103-3p is pivotal in lung tumorigenesis, as it directly targets PDCD10, influencing lung cancer cell proliferation and metastasis." (PMID 39540714, 2024).
retinoblastoma (3 papers, 2021 to 2022). A malignant tumor that originates in the nuclear layer of the retina. "Hypoxia-induced miR-181b promoted the angiogenesis of retinoblastoma (Rb, a malignancy originating from the retina) by downregulating programmed cell death-10 (PDCD10) and GATA binding protein 6 (GATA6)." (PMID 35626707, 2022). "One group identified that miR-181b was increased in retinoblastoma cells and enhanced angiogenesis through targeting programmed cell death-10 (PDCD10) and GATA binding protein 6 (GATA6)." (PMID 34356894, 2021). "Upregulation of miR-181b which is induced by hypoxia could increase angiogenesis of retinoblastoma cells by regulating PDCD10 and GATA6." (PMID 35402235, 2022).
breast tumor (2 papers, 2018 to 2021). "Given our observations that TRIM59 was up-regulated in human breast tumors and that TRIM59 stabilizes PDCD10 protein, we asked whether PDCD10 is essential for breast tumor growth and if the expression of PDCD10 is correlated with TRIM59." (PMID 30408026, 2018).
cerebrovascular disease (2 papers, 2020 to 2022). "The NGS data analysis was performed in two steps: initially we considered the three known CCM genes, namely KRIT1 (CCM1), CCM2 and PDCD10 (CCM3), and subsequently extended the analysis to NGS panels, including the “Cerebro” panel composed of 23 genes associated with cerebrovascular diseases." (PMID 35883785, 2022).
cholangiocarcinoma (2 papers, 2021 to 2022). A carcinoma that arises from the intrahepatic biliary tree (intrahepatic cholangiocarcinoma) or from the junction, or adjacent to the junction, of the right and left hepatic ducts (hilar cholangiocarcinoma). "In cholangiocarcinoma, the expression of PDCD10 was significantly correlated with the infiltration level of nine immune cell types." (PMID 36497468, 2022). "PDCD10 was reported to be upregulated in HCC and cholangiocarcinoma, which was associated with aggressive clinicopathological features." (PMID 36497468, 2022). "In conclusion, the results of the present study suggest that the cholangiocarcinoma (CHOL)-hub genes (SNX15, ATP2A1, PDCD10, BET1, and HMGA2) can be used as biomarkers of tumor progression, metastasis, therapy outcome, and poor prognoses of CHOL." (PMID 34831096, 2021).
osteosarcoma (2 papers, 2023). A usually aggressive malignant bone-forming mesenchymal neoplasm, predominantly affecting adolescents and young adults. "Compared with previous research findings, in this study, we found that the positive rate of PDCD10 was high in patients with osteosarcoma." (PMID 35848121, 2023). "A series of function assays such as CCK8, Wound healing test, Plate cloning formation assay, and Transwell were done to confirm how PDCD10 affects osteosarcoma." (PMID 35848121, 2023). "In order to explore how PDCD10 affects the proliferation and invasion of osteosarcoma, we analyzed relevant pathways by analyzing the GSE17679 database." (PMID 35848121, 2023). "In this study, it was found that the expression of PDCD10 was increased in the tumor tissue of patients with osteosarcoma through bioinformatics analysis." (PMID 35848121, 2023). "In this part, pLKO.1, PDCD10 sh3 and PDCD10 sh3/Flag PDCD10 cell lines were used to prove the effects of PDCD10 repeatedly on osteosarcoma." (PMID 35848121, 2023). "We used bioinformatics analysis, IHC, and clinical data to confirm the expression of PDCD10 and its correlation with prognosis in osteosarcoma." (PMID 35848121, 2023). "In this study, it was found that PDCD10 was highly expressed in patients with osteosarcoma, and it was closely related to patient prognosis." (PMID 35848121, 2023). "PDCD10 was highly expressed in patients with osteosarcoma and correlated with prognosis; PDCD10 knockdown inhibited osteosarcoma growth, proliferation, migration, and invasion; PDCD10 overexpression promoted osteosarcoma growth, proliferation, migration, and invasion." (PMID 35848121, 2023). "The results indicated that the positive rate of PDCD10 was high in patients with osteosarcoma." (PMID 35848121, 2023). "The WB results indicated that the overexpression of PDCD10 could inhibit apoptosis and promote the proliferation, migration, and invasion of osteosarcoma by activating the EMT pathway." (PMID 35848121, 2023). "Although an animal model of subcutaneous tumorigenesis has been constructed to prove its function, no animal assays of metastasis of osteosarcoma have been carried out, and the demonstration of the ability of PDCD10 to metastasize in osteosarcoma is insufficient." (PMID 35848121, 2023). "We also found that, in osteosarcoma, PDCD10 could inhibit tumor apoptosis and activate the EMT pathway to promote tumor progress." (PMID 35848121, 2023). "We wondered if PDCD10 could influence the progress of the osteosarcoma." (PMID 35848121, 2023). "In this study, it was proved that PDCD10 can inhibit cell apoptosis and activate the EMT pathway to promote the progress of osteosarcoma, which will provide new targets for future therapy." (PMID 35848121, 2023). "PDCD10 inhibited apoptosis and activated the EMT pathway in promoting proliferation, migration, and invasion of osteosarcoma, which may provide a potential target for future bone tumor therapy." (PMID 35848121, 2023). "However, there are no relevant research reports on the effects of PDCD10 on osteosarcoma." (PMID 35848121, 2023).
Parkinson disease (2 papers, 2007 to 2009). A progressive degenerative disorder of the central nervous system characterized by loss of dopamine producing neurons in the substantia nigra and the presence of Lewy bodies in the substantia nigra and locus coeruleus. "This gene pair, consisting of the parkinsonism-related parkin gene (PARK2) and parkin co-regulated gene (PACRG) at chromosome 6q25.2-27, has many features in common with the PDCD10-SERPINI1 pair." (PMID 17212813, 2007). "It is of interest to note that the PREPL-C2ORF34 gene pair has several features in common with some other human bidirectional gene pairs such as the Parkinson's disease-related PACRG-PARK2 gene pair at 6q25.2–27, and the brain-disease related PDCD10-SERPINI1 gene pair at 3q26." (PMID 19575798, 2009).